IL1B (interleukin 1 beta)
Diseases named in the same sentence as IL1B in open-access papers (continued):
Sharing a sentence is not in itself a finding about the gene and the disease.
infection (continued). "On day 9 post infection, Pigeon04 induced mRNA expressions of IL1β and IL6 in 1 lung sample." (PMID 21826229, 2011). "Despite the fact that cell death involved plasma membrane permeabilization and coincided with IL-1β release, we conclude that necrosis induced upon infection of human macrophages with virulent Mtb secreting ESAT-6 over several days is independent of caspase-1 and cathepsin B." (PMID 21637850, 2011). "Infection of DCs from each donor (n = 3) with H37Ra consistently stimulated the release of pro- and anti-inflammatory cytokines including TNFα, IL-6, IL-8, IL-10, IL-1β and a modest increase in secretion of IL-12p70." (PMID 22024399, 2011). "Furthermore, early inflammatory responses in a murine lung model of infection were decreased in IL-1β knockout mice although bacterial clearance was similar when compared with wild-type mice." (PMID 21980402, 2011). "However, later in the infection process (8 hours) Nlrc4-/- cells secreted IL-1β at levels considerably higher than WT cells." (PMID 22241982, 2011). "Yet, mice treated later (days 2, 3 and 4 post-infection) showed significantly increased bacterial counts (p<0.05) relative to early-treated mice, indicating that IL-1β secretion is critical for initial host immune responses that limit bacterial proliferation in the lung." (PMID 21731762, 2011). "The recruited macrophages then secrete IL-1β, which induces expression of cell adhesion molecules on the endothelial cell surface through the NF-κB pathway to facilitate transendothelial migration of leukocytes to the site of injury/infection." (PMID 21886795, 2011). "Moreover, we indicated nDens of 2 genes induced and 2 genes repressed in all infection performed and nDens of all genes discussed above (IL-1β, IL-6, IL-12, TNF-α, IL-10, ADAM19, CCR7, CCL20 and IL-18)." (PMID 21436989, 2011). "Major genes related to fever induction, IL6 and IL1B, were still up-regulated (16-fold and 4-fold respectively) in infected udder quarters 24 h after infection although the inner body temperature was already declining and approached basal levels at this time point." (PMID 20184744, 2010). "The study also observed no induction of TNF-α and IL-1β after 36 h of infection, but the antimicrobial response gene encoding cytochrome b-245 (CYBB) was up-regulated." (PMID 20854687, 2010). "What all of these infections have in common is that caspase-1 activity, and thus IL-1β production, is dependent on the assembly of an inflammasome complex, although they may differ in their specific inflammasome components." (PMID 20195505, 2010). "In fact, IL-1β responses measured at very early times after infection in various mice supported this hypothesis." (PMID 21170303, 2010). "TLR activation upregulates transcription of proinflammatory cytokines interleukin-1β (IL-1β), tumor necrosis factor alpha (TNFα), and interleukin-6 (IL-6), which are essential for the recruitment of immune cells to the site of infection and controlling Mtb infection." (PMID 20808838, 2010). "In the ferret model with 27% mortality based on the >20% weight loss following infection with A/California/07/2009 pandemic influenza virus, sequential lung sampling documented decreased gene expression of CCL2, CXCL10, TNFA and IL1B on day 7 when animals show highest weight loss." (PMID 20957032, 2010). "Because IL-1β has significant pro-inflammatory effects, this feature may contribute to the dramatic difference in inflammation between wild type and ΔRD1 infections." (PMID 20463815, 2010). "IL-1β is produced mainly by macrophages after infection withInfluenza A." (PMID 21079759, 2010). "To test this hypothesis, we measured the concentrations of TNF-α and IL-1β in the bronchiolar alveolar lavage fluid (BALF) after IN infection with CO92 or CO92ΔyopH." (PMID 20565713, 2010). "We next studied the production of IL-1β during infection with M. leprae." (PMID 20671924, 2010). "A rapid oscillation of TNFα and IL1β in vivo occurs in response to infection." (PMID 20819226, 2010).
infection (continued). "Altogether, these data suggest that YopH is involved in delaying or inhibiting the expression of TNF-α and IL-1β during plague pneumonia and may be involved in the overall delayed inflammatory response to this infection." (PMID 20565713, 2010). "IL-1β is a powerful proinflammatory cytokine that is overexpressed in the presence of H. pylori and plays an important role in amplifying the inflammatory response to the infection." (PMID 20979650, 2010). "The other immunomodulatory gene, B16R, encodes a secreted glycoprotein of 50–60 kDa that is expressed at late times of the infectious cycle, and it functions as a viral soluble receptor for IL-1β (vIL-1βR) that blocks inflammatory and febrile host responses to infection." (PMID 20811493, 2010). "While IL-1β plays an important role in the inflammatory response against infection by increasing the expression of endothelial adhesion factors, thus allowing infiltration of leukocytes at the site of infection, IL-6 is a proinflammatory cytokine released in response to trauma or tissue damage." (PMID 22069560, 2010). "At one week post-infection, as expected, only pro-IL1β was present." (PMID 20808838, 2010). "In confirmation of this relevance, we and others previously showed that application of either IL-12 or IL-1β at the site of infection during the first three days after injection with L. major was able to promote Th1 differentiation and to inhibit disease progression in BALB/c mice." (PMID 20442861, 2010). "IL-1β is considered the prototypic multifunctional cytokine that affects nearly all cell types, either alone or in combination with other cytokines response to infection, injury, or immunologic challenge." (PMID 20858287, 2010). "Infection of Mφ1 with live Salmonella resulted in the production of IL-23, IL-18 and IL-1β." (PMID 20027291, 2009). "Importantly, the 1918 virus up-regulated key components of the inflammasome, NLRP3 and IL-1β, whereas these genes were down-regulated by A/Vietnam/1203/04 early after infection." (PMID 19798428, 2009). "However, mice supplemented with L. casei showed lower levels of TNF-α and IL-1β than the control group on d 5 post-infection." (PMID 19835595, 2009). "Similarly, within 24 hrs of infection, IL-1β was released by wild-type and caspase-7−/− macrophages in response to Salmonella typhimurium (Salmonella)." (PMID 19343209, 2009). "After vaccination, infection induced a large increase in expression of IFN-γ especially on days 1 and 8 p.i., whereas vaccination dampened the infection-induced increases in mRNA levels for the proinflammatory cytokines IL1-β, TNF, and IL-6 – in particular around peak parasitaemia." (PMID 19341445, 2009). "The studies of infection with the intracellular bacteria Rhodococcus equi have demonstrated that galectin-3 may regulate the innate immune response by diminishing IL-1β production by macrophages." (PMID 19229338, 2009). "Previous studies have demonstrated elevated IL-1β mRNA levels during both disease and infection." (PMID 18628987, 2008). "In a macrophage model of infection the changes in cell surface structures in hVISA/VISA strains were associated with significantly reduced NF-κB activation resulting in reduced TNF-α and IL-1β expression." (PMID 18304359, 2008). "The cytokine interleukin 1 beta (IL-1β) is a potent mediator in response to infection and injury." (PMID 18710581, 2008). "Il1a and Il1b transcription was measured four hours post-infection." (PMID 19043549, 2008). "Pro-inflammatory cytokines such as IL-1β, IL-4, IL-6 and IL-7 participate in this infection." (PMID 17935610, 2007). "IL-1β was found only after 10 and 20 h of infection, and IL-7 level was elevated only after 5 h." (PMID 16834785, 2006). "IL-1b secretion at 72 h post-infection was increased, however." (PMID 15301687, 2004).
infection (continued). "Finally, we assayed cytokine secretion in HIEC-6 cells expressing NLRP6 and found that infection with wild-type L. monocytogenes elicited increased IL-1β secretion, while the levels of IL-1β release upon infection with Δhly L. monocytogenes were comparable to uninfected controls." (PMID 41266655, 2026). "Our bullfrog model reproduced these hallmarks: IL-1β and IL-8 transcripts rose sharply then gradually declined as cytokine stores were exhausted, whereas the tight-junction proteins Claudin-7, ZO-2, and Occludin remained significantly down-regulated throughout infection." (PMID 40941293, 2025). "In this study, Il1b was identified as an essential response gene via systematic analysis, which indicates that Il1b may play a key immune role in macrophages against Brucella species at the early infection stage." (PMID 40427768, 2025). "After infection, the addition of FeSO4 significantly increased in the expression of jejunal IL-1β gene (p < 0.05); in the infected treated group, the addition of Fe-Gly significantly increased in the expression of jejunal IL-1β gene compared with the control group (p < 0.05)." (PMID 39944187, 2025). "Unlike, IL-1β that is constitutively expressed in human keratinocytes, IL-36 cytokines are expressed at low levels but are strongly upregulated in response to infection and psoriasis-associated cytokines, including IL-17A." (PMID 40121229, 2025). "The highest expression of IL-1β was observed following the infection of P. verrucosa, followed by P. submersa, which may suggest a heightened inflammatory response when these species are present in the infection." (PMID 40727705, 2025). "We observed that CL patients exhibit significantly higher levels of both ANXA1 and IL-1β in serum when compared to HS, reinforcing the hypothesis that ANXA1 may play an important role in modulating the systemic inflammatory response associated with infection." (PMID 41200163, 2025). "While it promotes IL-18 and IL-1β secretion, which may help control the infection, it can also lead to harmful outcomes—such as increased neutrophil recruitment and a TH2-biased immune response—that support parasite survival, particularly in L. major infection." (PMID 40794782, 2025). "Infection with HTLV-1A/CoI-L resulted in low overall frequency of monocytes, DCs, and neutrophils producing IL-10, with elevated frequencies of those producing TNF-α in both compartments, linked to high expression of IL-6, CCL2, and IL-33 in blood and of MMP1, IL-1β, CCL3, and CCL19 in the lung." (PMID 41006234, 2025). "Furthermore, it has been shown that IL-1β is detectable in the lavage fluid of CF children (mean range of 3.8 years of age) in the absence of any infection, which is associated with enhanced NE activity and worsened structural lung damage." (PMID 40791588, 2025). "Similarly, IL-1β, another key pro-inflammatory mediator, drives the local immune response and induces fever, pain, and further inflammatory cascades, while IL-8 facilitates the recruitment of neutrophils to sites of injury or infection." (PMID 41281271, 2025). "Once activated, these cells secrete proinflammatory cytokines, including TNF-α, IL-6, IL-1β, and IL-12 in proportions that vary according to fungal morphology, promoting an environment that favors the differentiation of Th1 and Th17 lymphocytes in the early stages of infection." (PMID 41590416, 2025). "Each species manifests a distinct cytokine profile: while certain strains of L. major (such as LmSd) trigger a robust IL-1β response that contributes to lesion pathology, L. amazonensis suppresses the initial production of inflammatory cytokines, facilitating the establishment of the infection." (PMID 41200163, 2025).
infection (continued). "The upregulation of IL-1β expression by T. pyogenes may similarly facilitate the establishment of infection, as a study showed that intrauterine infusion of T. pyogenes resulted in a significant increase in the percentage of polymorphonuclear neutrophils in the uterus samples of challenged cows." (PMID 40568580, 2025). "However, while viral loads at 6 dpi were similar between Il-1β–/– and Il-1r–/– animals, the reduction in cytokines was preserved, continuing for 6 days post-infection with SARS-CoV-2 P21, and was more profound at later time points in IL-1β deficient mice compared to Il-1r–/– and WT animals." (PMID 40016339, 2025). "However, ageing affects monocyte metabolism, which may have downstream effects on cellular responses to infection such as cytokine production, in particular IL‐1β." (PMID 40320615, 2025). "Therefore, the levels of IL-6 and IL-1β are higher during infection and inflammation." (PMID 39858184, 2025). "Caspase-1 catalyzes the conversion of pro-inflammatory cytokines, such as IL-1β and IL-18, into their biologically active forms, which are then released from the cell to initiate inflammatory responses and recruit immune cells to the location of infection or damage." (PMID 40784044, 2025). "Similarly, levels of TNF-α and IL-1β were lower in 3d mice early in infection." (PMID 40248691, 2025). "However, since all three cytokines play an important role in host defense against infection as well as in the pathogenesis of autoimmune and inflammatory diseases, a therapy that concomitantly targets the release of IL-1α, IL-1β and IL-18 is of high clinical interest." (PMID 41221292, 2025). "IL-1b is an important mediator of the inflammatory response, and is produced by a wide range of cell types early after the activation of host pattern recognition receptors (PRRs), enabling a response to infection by the induction of a reactions cascade that leads to inflammation." (PMID 41009783, 2025). "Similarly, the CANTOS trial and related studies using IL‐1β monoclonal antibodies demonstrated that targeting chronic inflammation reduced cardiovascular risk, particularly in CKD patients, although at the cost of increased infection‐related mortality." (PMID 40810380, 2025). "Similarly, il-1β and tnf-α, as proinflammatory cytokines, are crucial for immune regulation, with il-1β activating lymphocytes and phagocytes and tnf-α being one of the earliest genes expressed during infection." (PMID 40988649, 2025). "In concurrence with the pro-inflammatory gene expression, M1 macrophages expressing IL-1β, Tlr2, and Nos2 clustered around Candida, while despite higher expression of anti-inflammatory genes, M2 macrophages were largely omitted from within the infection niche and rather present around it." (PMID 40586608, 2025). "Additionally, we observed that ΔnleB/espL triggered enhanced macrophage cytotoxicity, caspase-8 and caspase-1 processing, GSDMD cleavage and IL-1β maturation compared to ΔnleB infection in LPS-primed macrophages, while ΔnleB/espL complemented with nleB or espL caused less cell lysis (Fig. EV5A)." (PMID 40128366, 2025). "Previous studies have shown that infection with highly virulent ASFVs including E70 (genotype I, Europe), Armenia 2008 (genotype II, Caucasus), and SY18 (genotype II, China) can cause increases in serum IL-1α and IL-1β, while moderately virulent and attenuated ASFV strains do not." (PMID 41156603, 2025). "Additionally, the infection induced upregulation of the pro-inflammatory cytokines such as interleukin-1beta (IL-1β) and interleukin-6 (IL-6), and downregulation of the anti-inflammatory cytokines such as interleukin-10 (IL-10) and transforming growth factor beta (TGF-β)." (PMID 40571943, 2025). "Therefore, we hypothesized that the transcriptional modulation of NLRP3 in the first three hours of infection is essential for subsequent IL-1β activation by the NLRP3 inflammasome." (PMID 38248981, 2024).
infection (continued). "Generally, infection, tissue damage, or exposure to endotoxins could cause activated M1 macrophages following the production of various pro-inflammatory mediators, such as inducible nitric oxide synthase iNOS, NO, COX-2, TNF-α, IL-1β, and IL-6." (PMID 38393066, 2024). "Notably, after infection, IL-1β expression in ASC-KO was significantly lower than in WT cells." (PMID 38707903, 2024). "Interestingly, the stimulation of pancreatic islets with very high concentrations of TNF, IFNγ and IL-1β inhibited insulin secretion, indicating that during severe, life-threatening infection these cytokines are involved in facilitating stress-induced hyperglycemia." (PMID 39107476, 2024). "Moreover, IL-18 may also promote the secretion of other pro-inflammatory cytokines such as TNF-α, IL-1β, IL-8, and GM-CSF, which leads to an increase in the expansion, migration, and activation of neutrophils during infections." (PMID 39042701, 2024). "To confirm that infection with A. actinomycetemcomitans triggers the release of IL-1β from macrophages, we checked the activation of inflammasomes in macrophages, which regulate IL-1β maturation following caspase-1 activation in response to infection with A. actinomycetemcomitans." (PMID 39143049, 2024). "Furthermore, gene expression of TNF-α, IL-1β, IL-6, and IL-8 were also significantly upregulated 1 to 5 h after infection by K. pneumoniae, although SeMet reduced inflammation and protein expression of TLR4, Ikappa-B, NF-κB, and TNF-α in bMECs and macrophages infected with ESBL E. coli." (PMID 39456758, 2024). "This infection leads to chronic inflammation, which may accelerate carcinogenesis through the secretion of proinflammatory cytokines such as TNF-alpha, IL-1β, and IL-6, which in turn increase the risk of DNA damage and mutations, which promotes the transformation of cancer cells." (PMID 39451226, 2024). "Thus, high activation of innate immunity receptors (TLR4, TLR6) and inflammatory cytokines (such as pro-IL-1β) in Swiss mice during the acute phase of infection may contribute to the low parasite burden." (PMID 38896633, 2024). "Due to the change in the ROS and RNS production during BMDMs infection with Mtb and RvΔ0687, we further hypothesized this could impact the secretion of cytokines or chemokines and analyzed the levels of IL-1β, TNF-α, MIP-1α and IP-10 cytokines in the supernatants of BMDMs infected with Mtb strains." (PMID 39063103, 2024). "Finally, we wanted to determine whether the link between the complement system, IL-1β and life-threatening infection, which we show here in mice, is also relevant for human disease." (PMID 38236896, 2024). "IL-1β rapidly recruits neutrophils to sites of inflammation, activates endothelial adhesion molecules, induces cytokines and chemokines, triggers fever responses, and stimulates specific adaptive immunity, such as Th17 responses, contributing to anti-infection mechanisms." (PMID 39595526, 2024). "However, the use of these materials as therapeutic treatments could reduce IL-1β mRNA expression only following the secondary infection." (PMID 38492183, 2024). "After poly(I:C) infection, there was a downregulation of Uchl1 expression, while the expression of Tlr3, Caspase3, Caspase12, NOD-like receptor thermal protein domain associated protein 3 (Nlrp3), Interleukin-1β (IL-1β), IL-6, and Tumor necrosis factor alpha (Tnfα) was significantly upregulated." (PMID 38300431, 2024). "Furthermore, whether NLRP3 inflammasome assembling is required during in vivo infection with T. crassiceps must properly be studied, since we found that both IL-1β and IL-18 are differentially released during T. crassiceps infection." (PMID 38842647, 2024). "In the current study, we found that B5 promoted the mRNA expression of TNF-α and IL-1β in the early infection phase, but inhibited the secretion of TNF-α, IL-1β, and IL-17 in the later infection phase, suggesting that B5 could regulate inflammatory response induced by K. pneumoniae." (PMID 39408834, 2024).